IL5 (interleukin 5)
Diseases named in the same sentence as IL5 in open-access papers (continued):
Sharing a sentence is not in itself a finding about the gene and the disease.
helminth infection (continued). "IL-5 is an important cytokine in the differentiation and activation of anti-parasitic eosinophil responses and has been specifically targeted in mice to demonstrate the in vivo role of eosinophils in helminth infections, as discussed in previous reviews." (PMID 31839015, 2020). "In addition, a review by Behm and Ovington (2000) highlighted that IL-5 and eosinophils have different impacts on different helminth infections." (PMID 31839015, 2020). "This becomes important where asymptomatic helminth infection profoundly affects the immune phenotype of TB patients with a strong bias towards Th2 types of immune response, such as increased regulatory T cells as well as IL-5 and IL-10 secreting cells." (PMID 32498074, 2020). "Besides that, adoptive transfer of Zeb1 KD cDC1 MutuDCs clears helminth infection by inducing IL-13 and IL-5 secreting Th2 cells in MLNs of infected animals." (PMID 30483264, 2018). "IL-5 plays a major role in the regulation of eosinophil formation, maturation, recruitment and survival; eosinophils have been identified as important contributors in the control of helminth infections in mammalian hosts." (PMID 28708895, 2017). "Helminth infections in human host cause an immune response associated with elevated levels of IgE, tissue eosinophilia and mastocytosis, and with the presence of CD4+ T cells that preferentially produce IL-4, IL-5, and IL-13." (PMID 27980457, 2016). "We found that concomitant asymptomatic helminth infection profoundly affects the immune phenotype of TB patients with a strong leaning towards Th2 types of immune response such as increased regulatory T cells as well as IL-5 and IL-10 secreting cells." (PMID 26248316, 2015). "However, IL-5 and IL-13 cytokine responses to Ascaris worm challenge were detectable in all subgroups with evidence of helminth infection (eggs or high IgE)." (PMID 25209883, 2014). "IFN-γ and IL-5 are well known players in innate, adaptive and vaccine-induced immunity against helminths, with the adaptive type 2 response referred to as “typical” for helminth infections." (PMID 22413031, 2012). "Other evidence for the role of eosinophils in helminth infection are from experimentally infected mice that have been depleted of eosinophils by IL-5 neutralization and/or gene targeting and the observation that eosinophil levels increase after they are infected with helminths." (PMID 19308259, 2009). "In general, helminth infections develop a Th2-type immune response with an increase in IL-4, IL-5, IL-13 and IL-33 cytokines, which may assist in the expulsion of worms in the lungs, but there are still no studies on the importance of the cytokine IL-33 in T. canis infection." (PMID 34324507, 2021). "NK cells have been shown to produce significant amounts of IL-5, which contributes to eosinophil recruitment in an in vivo mouse model of allergic inflammation, and may also be involved in T-cell-independent eosinophil recruitment after helminth infections." (PMID 25074012, 2014). "Therefore, IL-5 might be an important cytokine against helminth infection." (PMID 37501169, 2023). "IL-25 is released from intestinal tuft cells stimulated by helminth infection, and acts on ILC2 cells to release type 2 cytokines, including IL-5 and IL-1343." (PMID 35288645, 2022). "IL4 has distinct functions in helminth infections but there is considerable redundancy with IL13, IL5 and IL9, whose contributions also vary among systems and parasite species/strains." (PMID 33226981, 2020). "Th2 cells remain a minor population of IL-5 and IL-13 producing cells within the VAT even during helminth infection." (PMID 30792718, 2019). "The most common source of IL-5 is “type 2” CD4+ helper T cells, either in the setting of an immune response to an environmental agent or pathogen (e.g., allergy and helminthiasis), or in the setting of T cell lymphoma (e.g., Sezary syndrome)." (PMID 29682504, 2018).
helminth infection (continued). "IL-5 and IL-13, produced by ILC2, can recruit eosinophils which are essential for the clearance of helminth infections." (PMID 29354125, 2017). "Clinical trial exclusion criteria ensure that patients have no helminth infections; therefore, cases of parasitic infection while on dupilumab or IL-5 agents are exceedingly rare." (PMID 40843371, 2025). "It was later shown that innate lymphoid cells could respond to the tissue alarmin TSLP to produce IL-5 and IL-13, but this appears to occur mainly in the skin leaving the impact of TSLP in other stages of helminth infection less clear." (PMID 32793230, 2020). "Notably, anti-CTLA-4 mAb administration also induced an increase in the Th2 cytokines IL-4 and IL-5, supporting both that Tregs mediate schistosomiasis pathogenesis, and that CTLA-4 regulates the Th2 response to worm infection." (PMID 31134084, 2019). "Although maternal filarial infection was associated with helminth-antigen specific TH2 responses, it was low maternal education or SES but not helminth infection, which was associated with the development of high total IgE and PHA-induced IL-5." (PMID 23566643, 2013). "Maternal Mansonella perstans infection was associated with higher interleukin (IL)-10 responses to both immunogens but no reduction in gamma interferon (IFN-γ), IL-5 and IL-13 responses; other maternal helminth infections showed little effect." (PMID 21040693, 2010). "Five mothers had a positive IL-5 response to CFP; all had helminth infections." (PMID 16371154, 2005). "Nine infants had positive IL-5 responses to CFP; 6 had mothers with helminth infection." (PMID 16371154, 2005). "In a helminth infection model, mice lacking CCR8 exhibit reduced type 2 cytokines IL-5, IL-13, and IL-9, and greater worm burden in the small intestine." (PMID 35707544, 2022). "We analyzed IFN-γ, IL-5 and IL-10 secreting cells from a subset of 30 HIV negative TB patients and 56 CCs with and without helminth infection." (PMID 26248316, 2015). "To confirm whether type 2 cytokines IL-4, IL-5, IL-9, and IL-13 contributed to helminth-induced protection against TNF-α and IFN-γ shock, we compared the levels of cytokines in the presence or absence of the helminth infection." (PMID 38727220, 2024).
atopic dermatitis (84 papers, 2006 to 2025). "In the skin, ILC2-derived IL-5 is implicated in the strong eosinophil infiltrate observed in an IL-33 transgene-driven model of atopic dermatitis in mice." (PMID 38030609, 2023). "The onset of atopic dermatitis is due to an antigen disturbing the balance of Th1/Th2 cytokines to cause overproduction of Th2 cytokines such as IL-4, IL-5, and IL-13, while stimulating the B cells to increase the serum IgE level." (PMID 35694270, 2022). "Application of dTBP2 inhibited the mRNAs levels of proinflammatory cytokines such as IL-6 well as Th2-related cytokines/chemokines associated with pathogenesis of atopic dermatitis including IL-4, IL-5, IL-13, TSLP, MCD, and TARC." (PMID 28134765, 2017). "For example, in patients with atopic dermatitis, acute lesions are associated with increased IL-4 mRNA with lymphocytic infiltration, whereas chronic lesions have a predominance of IL-5 mRNA with eosinophil infiltration." (PMID 24971469, 2014). "Several markers are employed to measure the severity of clinical symptoms of experimental atopic dermatitis including degree of scratching, pruritic skin lesion, and levels of pathogenic cytokines including IL-4, IL-5, IL-13 and IFN-γ." (PMID 24499290, 2013). "Atopic dermatitis has been associated with the Th2 phenotype and dominance of IL-4, IL-5, and IL-13 secretion." (PMID 21303540, 2011). "Additionally, reports have linked nemolizumab to exacerbations of atopic dermatitis (AD), BP, and urticaria - conditions primarily driven by Th2 cytokines such as IL-4, IL-5, and IL-13." (PMID 40104458, 2025). "Chronic ILC2 activation was reported to contribute to a large variety of tissue inflammatory disorders such as asthma in the lung and atopic dermatitis in the skin, which are generally associated with over-production of the type 2 inflammatory cytokines such as IL-4, IL-5, and IL-13." (PMID 28271445, 2017). "Interleukins IL-4, Il-5, IL-10, IL-13 and IL-33 play an important role in atopic dermatitis patients." (PMID 40771803, 2025). "We find that in RAG-deficient mice, ILC2 populations expand and produce increased IL-5 and IL-13 at steady state and contribute to increased inflammation in atopic dermatitis (AD)-like disease." (PMID 38712036, 2025). "The late-stage atopic dermatitis–asthmatic pattern is defined as immune dysregulation driven by Th2 cells, characterized by elevated levels of interleukin (IL)-4, IL-13, and IL-5." (PMID 41155390, 2025). "Intrinsic atopic dermatitis is characterized by a normal skin barrier, lower expression of IL-4, IL-5, and IL-13, and higher expression of IFN-gamma." (PMID 38672221, 2024). "In the context of eczematous dermatitis, the inflammatory milieu is often dominated by a Th2‐driven immune response, characterized by cytokines such as IL‐4, IL‐5, and IL‐13." (PMID 39670074, 2024). "Atopic Dermatitis is largely a Th2-driven disease that is characterized by elevated levels of interleukin (IL)-4, IL-5, IL-13, and IL-31." (PMID 39119011, 2024). "Atopic dermatitis is defined as an immune disorder driven by Th2 cells and characterized by elevated levels of interleukin (IL)-4, IL-13, and IL-5." (PMID 38541664, 2024). "Atopic dermatitis generally occurs due to an abnormal increase in the levels of Th2 cytokines such as IL-4, IL-5, and IL-13." (PMID 37432237, 2023). "The enrichment of the immune pathways was also high in atopic dermatitis or psoriasis, but the IL-3/IL-5/GM-CSF and IL-4/IL-13 signaling was highest in HS lesional skin." (PMID 38069342, 2023). "TQ was recently discovered to attenuate atopic dermatitis by reducing the levels of inflammatory cytokines, such as IL-4, IL-5, and IFN-gamma, and immunomodulatory cells in the blood." (PMID 36518853, 2022). "Atopic dermatitis is associated with T-cells exhibiting a Th2 polarized phenotype, with increased expression of Th2 cytokines, such as IL4, Il5, and IL13." (PMID 34445339, 2021).
atopic dermatitis (continued). "It was reported that 60% ethanol/water extraction of P. densiflora bark regulated wound healing-involved cytokines such as interleukin (IL)-4, IL-5, and tumor necrosis factor alpha, resulting in attenuated atopic dermatitis." (PMID 32325920, 2020). "In atopic dermatitis, Th2 cytokines such as IL-4 and IL-5 are known to have an important function in amplifying allergic inflammation in skin lesions." (PMID 32514255, 2020). "The activation of T2 cells leads to IL-4, IL-5, and IL-13 secretion, provoking skin barrier alteration, immune cell infiltration into skin, and itch as observed in atopic dermatitis." (PMID 31028434, 2019). "Atopic dermatitis increased the expression levels of cytokines/chemokines, such as interleukin-5 (IL-5), macrophage inflammatory protein-1ß (MIP-1ß), MIP-2, chemokine (C-C motif) ligand 5 (CCL5), and IL-17, in BALB/c mouse." (PMID 30459600, 2018). "Atopic dermatitis increased the expression levels of IL-5, IL-17, chemokine (C-C motif) ligand 5 (CCL5), MIP-1ß, and MIP-2 in the serum of BALB/c mouse." (PMID 30459600, 2018). "Atopic dermatitis has been thought as a typical Th2 type immune disorder that expresses high levels of Th2 type cytokines such as IL-4, IL-5, and IL-13." (PMID 24499290, 2013). "Atopic dermatitis is thought to be a typical Th2 type immune disorder which shows elevated serum IgE level and increment of Th2 type cytokines such as IL-4, IL-5 and IL-13." (PMID 22988890, 2012). "Th2 cells release cytokines, such as IL-4, IL-5, and IL-13, in allergic inflammation and atopic dermatitis." (PMID 21303540, 2011). "The role of interleukins IL-4, IL-5, IL-10, IL-13 and IL-33 in atopic dermatitis." (PMID 40771803, 2025). "While CSU and atopic dermatitis (AD) can be clinically distinguished by specialist clinicians, they share significant similarities in their inflammatory mechanisms, particularly in the role of pro-inflammatory cytokines like IL-4, IL-5, IL-13, and IL-31." (PMID 38396704, 2024). "Similarly, the JAK-STAT signaling pathway is utilized by IL-4, IL-5, and IL-13 to induce Th2 immunity in Atopic Dermatitis." (PMID 39119011, 2024). "For instance, high amounts of thymic stromal lymphopoietin (TSLP) in patients with atopic dermatitis activate T helper (Th) cells to produce Th2 cytokines (e.g., Interleukine (IL)-4, IL-5), which in turn can directly lead keratinocytes to further produce more TSLP." (PMID 37511139, 2023). "In addition, a group of IL-5 and IL-13-producing resident ILC2s have been observed in the skin of healthy humans and increased in samples from patients with atopic dermatitis, as well as in a murine model of the same condition." (PMID 34759931, 2021). "We can hypothesize that, in atopic dermatitis, the axis IL-4-IL-13 is crucial in the pathogenesis of skin inflammation while IL-5/eosinophyl pathway is dispensable." (PMID 34680614, 2021). "Although S. aureus colonization has been strongly associated with atopic dermatitis, which is driven by Th2 responses, most components of the Th2 response such as IL-4, IL-5, and IL-13 were not induced by early colonization of S. aureus." (PMID 30185226, 2018). "In atopic dermatitis, Th2 cells were leading to excessive IL-5 productions." (PMID 25861366, 2015). "Given increased levels of type 2 cytokines, IL-13, IL-4 and IL-5, in acute atopic eczema lesions and enhanced production of epithelial cytokines IL-33, IL-25 and TSLP, it is plausible that group 2 innate lymphoid cells contribute to the pathogenesis of atopic dermatitis." (PMID 25427661, 2014). "Th2 cells produce IL-4, IL-5, and IL-13 and play major roles in acute atopic dermatitis." (PMID 24499290, 2013). "An immunohistochemical examination of the skin lesions in NC/Nga atopic model mice revealed the typical features of affected skin observed in patients with atopic dermatitis, such as increased infiltration of T cells, mast cells, and substantial expression of IL-4 and IL-5." (PMID 21303540, 2011).
atopic dermatitis (continued). "Atopic and allergic conditions, including atopic dermatitis, food allergies, atopic asthma, and allergic rhinitis, are all mediated by a Th2-type immune reaction, which involves the IgE antibody response, IL-4 and IL-5 cytokines, and tissue infiltration with eosinophils and mast cells." (PMID 38540315, 2024). "Furthermore, RTX therapy could improve cutaneous lesions in atopic eczema patients through reducing IL-5 mRNA expression and IL-5-expressing CD4+ T-cell numbers in the skin, lowering Th2 frequencies and eosinophil counts in the blood." (PMID 34640595, 2021). "Recently, inhibition of IL-5 signaling via JAK2 has been reported to be effective in bronchial asthma and atopic dermatitis." (PMID 37000107, 2023). "Other targets in phase III trials included IL-4/13 (n = 1 for atopic dermatitis, prurigo nodularis, and CSU, respectively), IL-5 (n = 1 for bullous pemphigoid), and IgE (n = 1 for CSU)." (PMID 35529441, 2022). "A recent study observed that MIF amounts were increased in the allergen-induced skin tissue of atopic dermatitis murine models, and the elevated MIF levels promoted the secretion of IL-4 and IL-5, and eosinophil recruitment in the skin." (PMID 34305594, 2021). "Ta-EE suppressed the mRNA expression of T helper 2-specific cytokines, IL-4 and IL-5, and the proinflammatory cytokine IFN-γ in the atopic dermatitis skin lesions of AD mice." (PMID 29736153, 2018). "In a mouse model of atopic dermatitis induced by topical application of Calcipotriene (a synthetic Vitamin D3 derivative), ILC2-derived IL-5 and IL-13 were reported to play an important role in promoting the disease development." (PMID 28271445, 2017). "High levels of TSLP, but also of IL5 and IL13 have been reported in the skin of atopic dermatitis patients, particularly in those with elevated IgEs." (PMID 27431613, 2016). "In conclusion, using mice and ovalbumin mimicking allergic dermatitis and using IBH, a natural equine skin allergic disease, we demonstrated that IL‐5 vaccination significantly decreased allergen‐specific IgE levels, together with Th1/Th2 cytokines, such as IL‐4 and IFNγ." (PMID 40838325, 2025). "By contrast, atopic dermatitis and Th2-related genes, including Il4, Il5, Il13 and Il31 were lowly expressed or not detected at all, and other atopic dermatitis-related transcripts (Ccr4, Ccl17, Ccl24) were not significantly differentially expressed." (PMID 38528069, 2024). "The IFNG and IL5 methylation rates were higher among exclusively breastfed infants with atopic dermatitis compared to the non-breastfed." (PMID 37520545, 2023). "Patients with atopic dermatitis show increased expression of Klrg1 and the interaction of activated ILC2s with E-cadherin results in a down regulation of GATA-3, IL-5, IL-13, amphiregulin and reduced ILC2 proliferation; suggesting a negative regulatory role for Klrg1 in skin ILC2s." (PMID 34759931, 2021). "Lastly, medically targeted cytokines known to drive inflammatory skin diseases such as psoriasis (IL-17, IL-22, and IL-23) and atopic dermatitis (IL-4, IL-5, IL-13) were not identified in healthy skin." (PMID 33154365, 2020). "In the case of atopic dermatitis ILC2 have been described to be the major proinflammatory ILC subtype accountable for the production of marker cytokines like IL-13 and IL-5, cross-talk with other innate cells like basophils and dendritic cells, and finally promoting the development of TH2 cells." (PMID 31781103, 2019). "In addition, Ta-EE suppressed the expression of T helper 2-specific cytokines, such as IL-4 and IL-5 and proinflammatory cytokines, such as IFN-γ and IL-12 in a transcriptional level in the atopic dermatitis skin lesions of the AD mice and total splenocytes." (PMID 29736153, 2018). "SEB selectively stimulates the production of interleukin-5 (IL-5) in patients with atopic eczema/dermatitis syndrome (AEDS) or allergic asthmatics but not in asymptomatic atopic or non-atopic individuals." (PMID 16952309, 2006).
atopic dermatitis (continued). "The immunomodulatory effects of probiotics can reduce the severity of atopic dermatitis by inhibiting Th2 cell responses, cytokines such as IL-4, IL-5, IL-6, and IL-13 are no longer secreted, INF-γ (cytokines released by Th1 cells) is decreased, phagocytosis is stimulated, and serum IgA increases." (PMID 39781533, 2025). "In patients without atopic dermatitis, anti‐IL5 biologics were the first‐line treatment in 59% of cases, whereas they were only prescribed as the first‐line treatment in 35% of patients with comorbid atopic dermatitis." (PMID 40662227, 2025). "Moreover, many of the novel treatment strategies in allergic disorders (e.g., atopic dermatitis) and chronic respiratory diseases (severe eosinophilic asthma, EGPA, eosinophilic COPD, HES) specifically target eosinophils (i.e., mepolizumab/anti-IL-5 mAb or benralizumab/anti-IL-5R mAb)." (PMID 39409176, 2024). "In addition, while dupilumab is highly effective in controlling atopic dermatitis, no data are available regarding anti-IL-5/IL-5R monoclonal antibodies." (PMID 34680614, 2021). "Additionally, we examined the effects of ALBE on the expression and secretion of Th2 cytokines, such as IL-4 and IL-5, in primary murine splenocytes using RT-PCR and ELISA assays to investigate the further involvement of ALBE in Th2 functions in the atopic dermatitis-like skin lesions." (PMID 21303540, 2011).